CCND1 (cyclin D1)
Diseases named in the same sentence as CCND1 in open-access papers (continued):
Sharing a sentence is not in itself a finding about the gene and the disease.
breast cancer (continued). "Among women, the most common type of breast cancer is the hormone receptor-positive/human epidermal growth factor receptor 2 negative (HR+/HER2−-) breast cancer, where CCND1 as an encoding of cyclin D1, the catalytic subunit of CDK4 and CDK6, is profoundly expressed." (PMID 34948218, 2021). "Interestingly, ncRNACCND1s can crosstalk with another lncRNA, namely, LINC00473, to fine-tune the expression level of CCND1 in breast cancer cells." (PMID 33868377, 2021). "IMX-158, an ER + HER2- breast cancer model, harbors an ESR1 mutation and CCND1 amplification." (PMID 33407601, 2021). "For example, NEAT1 induced breast cancer progression by regulating the miR-410-3p/CCND1 axis, indicating that NEAT1 may be a potential therapeutic target in breast cancer." (PMID 34956895, 2021). "Furthermore, experimental evidence has also shown elevated cyclin D1 protein levels and deposition of cyclin D3 in breast cancer samples." (PMID 33920506, 2021). "Moreover, CCND1 overexpression has been reported in several cancers including lung cancer, breast cancer, colon cancer, glioblastomas, melanomas, and oral squamous cell carcinoma, with an amplification rate of approximately 40%." (PMID 34063946, 2021). "Furthermore, P21CIPI and CCND1 were essential for MPA-driven breast cancer growth, both in vitro and in vivo." (PMID 34779589, 2021). "Strong evidence for an association between mitogenic signaling in the restraint of autophagy led to studies wherein the pro-mitogenic, collaborative oncogene cyclin D1, was shown to restrain autophagy in breast cancer cells by modulating the activation of AMPK." (PMID 34631530, 2021). "AMPK enhanced autophagy and in human breast cancer cells cyclin D1 restrained AMPK activity." (PMID 34631530, 2021). "In breast cancer we identified rearrangement hot spots near CCND1 and in glioma near CDK4 and MDM2 and could directly associate this with increased expression." (PMID 34891161, 2021). "On the basis of these findings, we speculated that Cyclin D1 expression was upregulated in NUDT5-highexpressing breast cancer tissues." (PMID 33571243, 2021). "Cyclin D1 overexpression is detected in a variety of tumors, especially in breast cancer." (PMID 33571243, 2021). "Amplification of HER2 facilitates hyperactivated signaling of RAS/RAF/MAPK kinases which in turn sharply upregulates cyclin D1, leading to dysregulation of the G1/S checkpoint that plays a crucial role in breast cancer, being overexpressed in 40% of most cases." (PMID 34572912, 2021). "They indicated that eugenol exhibits anti-breast cancer properties by triggering apoptosis through the induction of the intrinsic pathway, by increasing p21WAF1 expression, by inhibiting cyclin D1 and ERK1/2, p38 and NF-κB signaling pathways that were known to play a key role in oral carcinogenesis." (PMID 34158560, 2021). "NAP1L1 interacted with the HDGF, an oncogenic factor for tumors, and the latter subsequently recruited the key oncogenic transcription factor c-Jun, which finally induced the expression of cell cycle promoter Cyclin D1(CCND1) and thus the cell growth of breast cancer." (PMID 34774047, 2021). "Moreover, ERRβ was reported to exhibit inhibitory effects on the cell cycle via regulation of p18, p21cip and cyclin D1 in breast cancer cells." (PMID 34089362, 2021). "Interestingly, the STAT3/Cyclin D1 axis is activated in several cancer types including breast cancer." (PMID 35003089, 2021). "Indeed, E2-stimulated Cyclin D1 expression in ER+ve breast cancer cells largely relies on an enhancer element downstream of CCND1 coding sequence, corresponding to the predominant ER-α recruiting site." (PMID 33777765, 2021).
breast cancer (continued). "Therefore, in the present study SNPs of CCND1 were selected on basis of minor allele frequency (MAF) ranging from 0.0001 to 0.05 and computationally analysed in order to predict their impact on Cyclin D1 function and to evaluate their role in breast cancer." (PMID 33438725, 2021). "We identify recurrent derivative chromosomes derived from chromosomes 11 and 17 in breast cancer samples, with homogeneously staining regions for CCND1 and ERBB2, and double minutes and breakage-fusion-bridge cycles in glioblastoma multiforme and ovarian cancer samples, respectively." (PMID 33927198, 2021). "CCND1 has long been considered an oncogene and has been demonstrated to be amplified in 10-20% in one study while in another study CCND1 amplification was seen in 78.6% of breast cancer cases." (PMID 34350123, 2021). "Herein, we showed that CCT2 expression can upregulate MYC and CCND1 gene expression and promote metastatic-like behavior in luminal A breast cancer cells that are typically less aggressive than the basal-like/TNBC subtypes usually associated with MYC amplification." (PMID 33996588, 2021). "Through gain and loss of function and rescue experiments, we confirm that MIR200CHG regulates the expression of tumor-associated proteins CDKN2A, cyclin D1, cyclin E1, BCL2, BAX, MMP1, MMP2, and MRP1 by binding YB-1, thereby promoting breast cancer proliferation, invasion, and resistance." (PMID 34272387, 2021). "CCND1, the most important member of the cyclin family, is currently considered an oncogene and is overexpressed in human esophageal cancer, head and neck cancer, and breast cancer." (PMID 34521875, 2021). "Cyclin D1, a well-known oncogene, is upregulated in up to 50% of breast cancers, which promotes G1–S cell cycle progression by forming a complex with cyclin dependent kinases 4/6 (CDK4/6), leading to the Rb phosphorylation and dissociation of transcription factor E2F from the pRb-E2F complex." (PMID 33824311, 2021). "In addition, cyclin D1 and β-catenin were also predicted to be indicators of prognosis in breast cancer patients." (PMID 33911067, 2021). "Knockdown and overexpression experiments in hepatocytes and breast cancer cells demonstrated that cyclin D1 represses fatty acid oxidation by inhibiting peroxisome proliferator-activated receptor alpha (PPARα) activity, a nuclear receptor that induces fatty acid oxidation." (PMID 33494394, 2021). "Interestingly, FOXO3A inhibits cyclin D1 expression in colorectal cancer as well as breast cancer whereas GSK3 phosphorylates cyclin D1 on Thr286, leading to ubiquitination and proteasomal degradation of cyclin D1." (PMID 33540707, 2021). "This might be the case in breast cancers where CCND1 gene is overexpressed in at least 50% of incidences." (PMID 33777765, 2021). "Furthermore, NAP1L1 was observed to be an interaction factor of HDGF, recruiting the key oncogenic transcription factor c-Jun and thus inducing the expression of cell cycle promoter CCND1, which finally stimulated breast cancer proliferation." (PMID 34774047, 2021). "Likewise, elevated CCND1 expression (encoding the CDK4/6 binding partner, Cyclin D1) is associated with lower expression of MHC I genes in breast cancer patients." (PMID 34025662, 2021). "Up to 20% of breast cancers have amplification of CCND1 gene." (PMID 33139730, 2020). "Furthermore, Cyclin D1 is still necessary for the proliferation of tamoxifen-resistant breast cancer cells because small interfering RNAs (siRNAs) targeting Cyclin D1 blocked their cell growth." (PMID 33139730, 2020).
breast cancer (continued). "Moreover, many dysregulated signaling pathways can lead to overexpressed Cyclin D1 protein in nearly 50% of breast cancers, most being estrogen receptor (ER)-positive luminal subtype." (PMID 33139730, 2020). "In the breast cancer cell models, down-regulation of cyclin D1 was enhanced if OOS was combined with lapatinib, supporting that OOS may increase the efficacy of the latter standard of care drug." (PMID 32878230, 2020). "Modulation of Cyclin D1 levels accordingly to ERα expression could explain the double action of the adipokine adiponectin in breast cancer occurrence and progression." (PMID 33317149, 2020). "As membrane-associated cyclin D1 augments activity of the ERα/PI3K/Akt complex pathway, the cytoplasmic membrane pool of cyclin D1 may be a new target for ERα expressing breast cancer treatments." (PMID 32948740, 2020). "CCND1 copy number gain is more frequent in estrogen receptor (ER)-positive breast cancer." (PMID 33059724, 2020). "In addition, we also analyzed HERVs that were associated, by localization, with breast cancer development genes (BRCA1, CCND1, ATM, NBS1/NBN, RAD50, KRAS, PI3K/PIK3CA)." (PMID 33194615, 2020). "The inhibitory phosphorylation of GSK3β might enhance cell proliferation and migration via β-catenin/cyclin D1 signaling pathway in breast cancer." (PMID 32466334, 2020). "Thus, Cyclin D1 is regarded as an oncogenic driver in different types of cancers including breast cancer, lung cancer, and melanoma." (PMID 33317149, 2020). "These investigations suggest that anti-breast cancer therapy targeting cyclin D1 could be very specific to breast cancers depending on the activated pathways." (PMID 31884567, 2020). "Notably, authors demonstrate that miR17/20 inhibits breast cancer cellular proliferation by repression of Cyclin D1 translation, via a conserved 3’ untranslated region miRNA-binding site." (PMID 33317149, 2020). "Overexpression of the CDK4/6 partner cyclin D1 has been identified in a number of tumor types, such as mantle cell lymphoma (with a well-known translocation involving cyclin D1 in nearly 100% of these cases), non-small cell lung cancer, and breast cancer." (PMID 32033319, 2020). "Some cell cycle regulators have been reported to be involved in not only breast cancer progression but also in the stem-like cell activity of breast cancer cells; for example, inhibition of cyclin D1 or CDK4/6 increases or decreases the migration capacity of stem cells in breast cancer." (PMID 32050983, 2020). "Moreover, GSK3β inhibition resulted in a significant increase in the nuclear expression of Cyclin D1 in SHP2 knockout breast cancer cells." (PMID 32944401, 2020). "Moreover, DILA1-ASOs significantly increased ubiquitinated Cyclin D1 in MCF7-Re cells, suggesting that DILA1 inhibits the ubiquitination of Cyclin D1 and leads to upregulated Cyclin D1 protein in tamoxifen-resistant breast cancer cells." (PMID 33139730, 2020). "We speculate that the underlying mechanism of miR-20b-5p contributing to the malignant progression of breast cancer is that miR-20b-5p overall upregulates both CCND1 and E2F1 via bidirectional regulation." (PMID 33008330, 2020). "In addition, some studies have shown that overexpression of CCND1 promotes tumour cell invasion and metastasis in breast cancer and gastric cancer, leading to a poor prognosis." (PMID 32660514, 2020). "However, the explicit effects of E2F1 and CCND1 on chemoresistance of breast cancer remains poorly understood." (PMID 32796817, 2020). "This suggests that S100P promoted cell proliferation by activating CCND1 protein in breast cancer." (PMID 33042844, 2020). "Besides, in the Cyclin D1-induced mammary tumors, the miR-17/20 cluster appears upregulated, since Cyclin D1 is able to bind the miR-17/20 cluster promoter regulatory region." (PMID 33317149, 2020).
breast cancer (continued). "Likewise, quantitative polymerase chain reaction (PCR) analysis showed that the expression of Cyclin D1 mRNA was diminished in SHP2 knockout breast cancer cells, whereas that of Cyclin E1 was unchanged." (PMID 32944401, 2020). "Cyclin D1 is a demonstrated target gene of miR-17-5p in MCF-7 breast cancer cells." (PMID 32631271, 2020). "Moreover, induction of miR-34a expression by increasing the sensitivity of cancer cells to chemotherapy and reducing CCND1 mRNA has entered two simultaneous positive effects on breast cancer." (PMID 32660221, 2020). "Indeed, two tamoxifen-resistant breast cancer cell line models used in this study showed that Cyclin D1 protein was further increased in resistant cells." (PMID 33139730, 2020). "Importantly, breast cancer cells that survive lapatinib treatment show enhanced activation of cyclin D1/CDK4 complex, hence suggesting the importance of this pair for anti-HER2 response and subsequent relapse." (PMID 32164162, 2020). "Downregulation of BCL2 and cyclin D1 enhanced cisplatin sensitivity in breast cancer cell lines." (PMID 32660222, 2020). "Finally, we looked at PLK1 expression in CCND1-amplified as compared to CCND1-diploid tumours in the TCGA and Metabric breast cancer datasets." (PMID 32792481, 2020). "Previous reports showed that 20(S)-Rh2 could reduce the transcriptional activity of E2F by targeting cyclin D1 and CdK4/6, leading to G1/S cell cycle arrest and apoptosis in liver cancer and breast cancer cells." (PMID 32796841, 2020). "To further confirm that Cyclin D1 degradation induced by SHP2 loss occurred through the ubiquitin–proteasome pathway, we determined whether the deletion of SHP2 increased ubiquitinated Cyclin D1 in breast cancer cells." (PMID 32944401, 2020). "They found that the combination of DpC and tamoxifen effectively reduced cyclin D1, upregulated p27, and inhibited the proliferation of breast cancer cells, which may be helpful to overcome the drug resistance of tamoxifen." (PMID 33362547, 2020). "Levels of molecular markers associated with cell-cycle progression, CDK4 and Cyclin D1, also decreased following PGRMC1 silencing, whereas the expression of pro-apoptotic markers, Bax and cleaved-caspase 3, increased in both breast cancer cell lines." (PMID 32704174, 2020). "We observed a significantly decreased expression of p-Akt, p-PI3K, p-mTOR and subsequent decreased expression of FOXO, Cyclin D1 and Bcl-2 following levobupivacaine treatment which correlated with decreased breast cancer cells proliferation and increased apoptosis." (PMID 32807213, 2020). "Moreover, FOXO3a has been shown to inhibit breast cancer proliferation through transcriptional regulation of multiple proteins, including p21Cip1, p27Kip1, and cyclin D1." (PMID 31296961, 2020). "Cyclin D1 amplification is a common oncogenic event in breast cancer, especially in luminal tumors." (PMID 34968306, 2020). "Therefore, both increased expression of Cyclin D1 and ERα positivity are valuable indicators for the prediction of recurrence and prognosis for breast cancer patients." (PMID 33317149, 2020). "Fifty-two patients with CCND1 amplification were identified comprising of 14 melanomas, 11 head and neck carcinomas (HNCs), 11 bladder carcinomas, eight non-small-cell lung carcinomas, five breast carcinomas, three esophagogastric carcinomas, and one glioma." (PMID 32903763, 2020). "siRNA knockdown of STAT3 blocked macrophage-induced expression of breast cancer proliferative genes cyclin D1 and c-Myc, and of cytokines IL-6, CCL5, and MCP-1, demonstrating the essential role of STAT3 expression in conditioned macrophage-induced alteration of gene expression." (PMID 30736340, 2019). "We previously reported that CCND1 represents a target gene of DHT-activated AR in MCF-7 breast cancer cells, evidencing the existence of a functional Androgen Response Element within the CCND1 promoter, which mediates the DHT/AR inhibitory effects on basal breast cancer cell proliferation." (PMID 31684907, 2019).
breast cancer (continued). "Furthermore, the acute deletion of cyclin D1 or inhibition of CDK4/6 kinase activity using palbociclib blocked the progression of HER2-driven breast cancer in mice." (PMID 30959874, 2019). "Given that FOXO3 is a transcriptional repressor of CCND121, we next checked whether FOXO3 is involved in LINC01355-dependent reduction of CCND1 in breast cancer cells." (PMID 31243265, 2019). "Thus, our study uncovers several unrecognized inter-links among PIP5K1α, PI3K/AKT, ER and cyclin D1 in ER+ breast cancer." (PMID 30104711, 2019). "We investigated whether cyclin D1 and G9a expression was increased in human breast cancer and whether cyclin D1 correlated with increased G9a abundance in particular breast cancer subtypes." (PMID 30718920, 2019). "As a downstream target of microRNA-30a, EYA2 could boost the proliferation of breast cancer cells through driving G1/S cell cycle progression with up-regulation of cell cycle-related proteins cyclin A, cyclin D1, and cyclin E." (PMID 30761270, 2019). "Of note, we were unable to identify any ER+/HER2−/FGFR1-amplified breast cancer cells without associated CCND1 amplification." (PMID 30914635, 2019). "Cyclin D1 is a critical driver of tumorigenesis of breast cancer." (PMID 30665445, 2019). "In this study, we investigated the relationships of pathological response after neoadjuvant chemo-endocrine therapy with alterations in the Ki67 labeling index (LI), expression of cyclin D1 (CCND1) and progesterone receptor (PgR), and estrogen receptor (ER) activity in breast cancer." (PMID 31112577, 2019). "Firstly, Cyclin D1, a common Wnt target is preferentially expressed in luminal breast cancer, which is inconsistent with other Wnt targets, suggesting that Cyclin D1 amplification may occur in luminal subtype preferentially." (PMID 31462314, 2019). "Among different cyclins, cyclin D1 with oncogenic growth-promoting properties is probably the most extensively studied in breast tumors that its mRNA overexpression has been reported in more than 50% of breast cancer cases." (PMID 31608167, 2019). "LINC01355 arrested breast cancer cells at the G0/G1 phase by repressing CCND1." (PMID 31243265, 2019). "Surprisingly, Cyclin D1 was preferentially overexpressed in luminal breast cancer cell lines." (PMID 31462314, 2019). "Moreover, the knockdown of LINC00673 enhanced bax expression and reduced bcl-2 and cyclin D1 levels in breast cancer cells, confirming that LINC00673 is involved in apoptosis and cell cycle progression." (PMID 31623640, 2019). "In order to determine whether the induction of H3K9me2 at specific chromatin elements by cyclin D1 involved association of cyclin D1 with G9a, immune-precipitation was conducted of endogenous cyclin D1 in the human MCF-7 breast cancer cell line." (PMID 30718920, 2019). "Genes up-regulated in MCF-7 cells (breast cancer) over-expressing CCND1 gene." (PMID 31191821, 2019). "Indeed, the overexpression of cyclin D1 was capable of reducing the sensitivity of breast cancer cells to HER2-targeted agents." (PMID 30959874, 2019). "We wanted to find out whether the inhibition of the growth of ER(+)/AR(+) breast cancer cells of the other investigated sterols also results from down-regulation of cyclin D1." (PMID 31235695, 2019). "We propose that selective inhibition of calcineurin could be an effective method for treatment of breast cancer, and other types of cancer in which cyclin D1 is overexpressed." (PMID 31484966, 2019). "For instance, overexpression of cyclin D1 occurs frequently in breast cancer." (PMID 30959874, 2019). "Also, several STAT3-related proteins, such as survivin and cyclin D1, are found overexpressed in human breast cancer tissues." (PMID 31485222, 2019).